Y_RNA (Y RNA )
Gene: Miscellaneous RNA gene on chromosome 5 (65,123,369 to 65,123,474, forward strand). Ensembl gene ENSG00000207439.
Homologues: Orthologues: chimpanzee Y_RNA (98% identical), macaque Y_RNA (96% identical), pig Y_RNA (71% identical). Paralogues in human: RNY1P5 (84% identical), Y_RNA (84% identical), Y_RNA (83% identical), Y_RNA (82% identical), Y_RNA (81% identical), Y_RNA (80% identical), RNY1P6 (79% identical), Y_RNA (79% identical), RNY1 (78% identical), Y_RNA (78% identical), Y_RNA (77% identical), RNY1P1 (76% identical), and 92 more.